OR2J2 (olfactory receptor family 2 subfamily J member 2)
Description:
Odorant receptor.
Synonyms: OR6-8; hs6M1-6; dJ80I19.4; OR6-19; OR6.3.8; ORL684
Tractability: Antibody: its Gene Ontology location is reachable by antibodies, with high confidence; UniProt places it where antibodies can reach, with medium confidence; UniProt predicts a signal peptide or a membrane-spanning region.
Gene: Protein-coding gene on chromosome 6 (29,170,907 to 29,175,811, forward strand). Ensembl gene ENSG00000204700.
Subcellular location: Cell membrane
Pathways (Reactome):
Sensory Perception: Expression and translocation of olfactory receptors; Olfactory Signaling Pathway
Gene Ontology:
Molecular function: olfactory receptor activity; G protein-coupled receptor activity
Biological process: detection of chemical stimulus involved in sensory perception of smell; G protein-coupled receptor signaling pathway
Cellular component: plasma membrane; membrane
Genetic constraint (gnomAD): Loss-of-function variants: 12 observed, 17.01 expected, observed/expected ratio (o/e) 0.71, 90% interval 0.45 to 1.14. The upper end of that interval is the gene's LOEUF score, 1.14, which puts it in group 5 of 6, group 1 being the genes least tolerant of losing a copy. Missense variants: 333 observed, 384.24 expected, observed/expected ratio (o/e) 0.87, 90% interval 0.79 to 0.95. Synonymous variants: 122 observed, 144.3 expected, observed/expected ratio (o/e) 0.85, 90% interval 0.73 to 0.98.
Homologues: Orthologues: chimpanzee OR2J2 (97% identical), mouse Or2j3 (80% identical), rat Or2j3 (80% identical). Paralogues in human: OR2J1 (91% identical), OR2J3 (87% identical), OR2B6 (58% identical), OR2B2 (57% identical), OR2C3 (57% identical), OR2G3 (57% identical), OR2W3 (57% identical), OR2G2 (56% identical), OR2H2 (56% identical), OR2B3 (56% identical), OR2H1 (55% identical), OR2Y1 (55% identical), and 80 more.